INS (insulin)
Diseases named in the same sentence as INS in open-access papers (continued):
Sharing a sentence is not in itself a finding about the gene and the disease.
Insulin resistance (continued). "Taken together, animal studies are generally consistent in respect to the beneficial effect of CUR on insulin action in the liver, skeletal muscle, and adipose tissue in various models of insulin resistance." (PMID 29743988, 2018). "The proposed mechanism was that the reduced insulin resistance reduced the insulin secretion, thereby preventing/delaying the onset of beta cell exhaustion, and the drop off from the set insulin resistance–insulin secretion hyperbola." (PMID 30360536, 2018). "In order to understand insulin resistance, it is important to understand the basis of insulin action and its signaling cascades." (PMID 30602666, 2018). "Hepatic insulin resistance is somewhat peculiar as the effects of hepatic insulin signaling result in insufficient suppression of hepatic gluconeogenesis and decreased glycogen synthesis but increased lipid accumulation." (PMID 30692925, 2018). "Insulin resistance, a phenomenon involving the resistance to insulin-stimulated glucose uptake, is involved in the pathogenesis of type 2 diabetes, hypertension, and coronary heart disease." (PMID 30577478, 2018). "In the late nineties, studies on human patients on hemodialysis showing insulin resistance demonstrated that alkalinizing treatment with oral sodium bicarbonate (NaHCO3) significantly increased insulin sensitivity and secretion." (PMID 30598026, 2018). "We thereby precisely evaluated relationship of circulating SELENOP with both insulin resistance and insulin secretion." (PMID 30425271, 2018). "Gains in BMI and fat mass index were also similarly associated with higher inflammatory glycoprotein acetyls and fasting insulin, which marks insulin resistance, drives type 2 diabetes, and amplifies CHD and mortality risk." (PMID 30545453, 2018). "The potential involvement of brain insulin resistance in the development of glucose homeostasis impairment seen in AD patients is also supported by the known role of insulin signaling in energy metabolism regulation." (PMID 29403354, 2018). "On the other hand, MeMC (50 mg/kg) treatment showed lower HOMA-IR index compared to HFD control (P<0.01), as an indication of good insulin sensitivity or low insulin resistance." (PMID 30524684, 2018). "Insulin resistance is a condition in which the adipose and muscle tissues and to a lesser extent the pancreas, brain, liver and kidney are unable to respond to insulin." (PMID 30567565, 2018). "HFD-fed offspring of HFD-fed mothers had increased body weight, fat mass, and glucose intolerance with increased insulin, leptin, insulin resistance, and hyperphagia compared with offspring of chow-fed mothers." (PMID 29483369, 2018). "In conclusion majority of the overweight/obese PCOS patients showed higher insulin resistance, lower insulin sensitivity and elevated fasting insulin concentration vs. their normal weight counterparts." (PMID 30197771, 2018). "Studies have shown that high glucose level by stimulating reactive oxygen species (ROS) production damages β-cells and leads to impaired insulin release and insulin resistance." (PMID 29343256, 2018). "Glucocorticoids were originally named as such due to their potent and acute effects on glucose metabolism, where liver and muscle pathways for insulin signaling are rapidly and profoundly affected, creating a state of insulin resistance." (PMID 29524454, 2018). "Rosiglitazone (Rosi), known as a positive drug for the treatment of insulin resistance, significantly increased insulin-stimulated glucose uptake in 3T3-L1 adipocytes at the concentration of 1 μmol/L." (PMID 29967664, 2018). "A growing body of evidence suggests that the structural and functional integrity of the CNS is compromised in T2DM in the presence of excess insulin or under a condition of insulin resistance." (PMID 29950970, 2018).
Insulin resistance (continued). "One previous longitudinal study found an association between low concentrations of 25(OH)D in pregnant mothers and fasting insulin concentrations and insulin resistance in their children at 9.5 years of age." (PMID 30388966, 2018). "The oxidative stress by increased iron deposition in beta pancreatic and liver cells leads to insulin resistance, higher insulin secretion and glucose dysregulation." (PMID 30043289, 2018). "The aim of this work is to investigate the effect of electroacupuncture (EA) on insulin sensitivity in high-fat diet (HFD) induced insulin resistance (IR) rats and to evaluate expression of AMPK/ACC signaling components." (PMID 30524482, 2018). "Meanwhile, decreased fatty content and glucose balance in the liver are improved, so glucose tolerance is also improved, and there are less fructosamine formation and insulin need, leading to insulin resistance reduction, both in adipocytes and hepatic tissue." (PMID 30026756, 2018). "FBG and FSI were administered to evaluate glucose homeostasis and insulin secretion in response to glucose challenge and insulin resistance, respectively." (PMID 30097599, 2018). "In previous studies, insulin resistance was mainly assessed by surrogate parameters, whereas the present study employed the gold standard for assessment of insulin sensitivity." (PMID 30159333, 2018). "Abdominal visceral fat is particularly harmful because it impairs insulin metabolism and promotes insulin resistance." (PMID 29997675, 2018). "Excessive intake of FFA by hepatocytes leads to decreased insulin sensitivity and the development of insulin resistance (IR) and systemic hyperinsulinemia, which subsequently contributes to the development of peripheral IR." (PMID 30219068, 2018). "Diet-induced obese AnxA1-deficient animals showed increased adiposity, elevated glucose and insulin levels and development of insulin resistance." (PMID 30110341, 2018). "In this model, using incretin-drug-based vildagliptin in obese insulin-resistant rats ameliorated peripheral insulin resistance and improved brain insulin sensitivity and mitochondrial function." (PMID 29904371, 2018). "TNF-alpha interferes with insulin signaling to produce insulin resistance in the insulin signaling pathway and promotes apoptosis through NF-KB in the apoptosis pathway." (PMID 33385166, 2018). "It has been shown that angiotensin II interferes with insulin metabolic signalling, induces insulin resistance, and impairs insulin-stimulated glucose disposal." (PMID 30425742, 2018). "Significantly higher fasting insulin and homeostasis model assessment—insulin resistance (HOMA‐IR) levels were found in the PCOS group compared to those in the CON and HF groups (P < .05)." (PMID 29602230, 2018). "Peripheral insulin resistance has been shown to contribute to insulin resistance in the brain by reducing available insulin levels and increasing the levels of beta amyloid (Aβ) formation." (PMID 29462993, 2018). "Metformin increases insulin sensitivity, reduces insulin resistance, improves insulin action, and increases peripheral glucose uptake in type 1 diabetes." (PMID 29338714, 2018). "It has important roles in regulating insulin sensitivity and metabolism, and is inversely related to adipose mass and insulin resistance." (PMID 30108547, 2018). "The remaining 95% patients have T2DM, a metabolic disease with high pancreatic insulin production in the setting of insulin resistance." (PMID 30149797, 2018). "A foremost concern for people with insulin resistance is the progressive failure of pancreatic β-cell function (a major determinant of type 2 diabetes progression) and compromised insulin secretion." (PMID 29373583, 2018).
Insulin resistance (continued). "Excess hepatic intake of FFA leads to decreased sensitivity to insulin and the development of insulin resistance and systemic hyperinsulinemia, which increase the production of “hepatic” glucose." (PMID 30219068, 2018). "An excessive accumulation of reactive oxygen species results in oxidative stress, inflammation that interferes with insulin pathways, and increased insulin resistance." (PMID 30583546, 2018). "The principle etiologies of T2DM incorporate insulin resistance in target tissues, relatively insufficient secretion of insulin, and subsequent decline of pancreatic β-cell function." (PMID 29959408, 2018). "We therefore previously screened a large diabetic patient database (n = 5,221) for marked insulin resistance (≥ 100 U insulin/day) and BMI ≤ 27 kg/m2, and identified five partial lipodystrophy cases." (PMID 30319454, 2018). "In adipose tissues of mice with diet-induced obesity, there is an increase in macrophages observed in adipose tissues before there is a substantial increase in insulin levels characteristic for systematic insulin resistance." (PMID 29950926, 2018). "Both groups displayed greater liver-fat deposition compared to controls as well as signs of insulin resistance, such as increased fasting circulating insulin levels accompanied by alterations in glycaemia and increased HOMA-IR index." (PMID 29566703, 2018). "In parallel, overproduction of insulin and insulin-like factors under a state of insulin resistance promotes the proliferation of all cells, including cancers." (PMID 30567335, 2018). "Specifically, HTFC feeding increased circulating insulin and homeostatic model assessment– insulin resistance (HOMA-IR) in GFP-overexpressing mice, without altering fasting plasma glucose." (PMID 30135298, 2018). "While chemerin signalling enhances insulin secretion from pancreatic islets, contradictory results have been reported on how chemerin links to obesity and insulin resistance." (PMID 29848608, 2018). "In certain pathological conditions, such as T2D, insulin resistance occurs meaning, these tissues show an impaired biological response to either exogenous or endogenous insulin." (PMID 29549241, 2018). "In our study, insulin resistance and insulin secretion increased with rising serum UA levels in both men and women." (PMID 29568712, 2018). "The insulin sensitivity was calculated using the HOMA index of insulin resistance (HOMA-IR, homeostasis model assessment of insulin resistance) = fasting insulin (U/mL) × fasting glucose (mM)/22.5." (PMID 29636851, 2018). "AA is a strong inducer of insulin secretion, whereas its metabolites demonstrate a divergent contribution to insulin resistance, depending on the involved cells and tissues." (PMID 30360467, 2018). "Total cholesterol, HDL cholesterol, and hemoglobin A1c levels as well as fasting levels of triglycerides, insulin, and homeostasis model assessment insulin resistance were measured using standardized procedures." (PMID 30266080, 2018). "Inverse correlations of AA levels with glucose and insulin, in agreement with studies in other populations, further supports the link between high ω6-PUFA proportions and lower risk for insulin resistance." (PMID 30400149, 2018). "Surprisingly, AE mice fed a HFD maintained increased insulin levels to compensate for insulin resistance, which was reflected in islet hyperplasia and improved glucose tolerance compared to SPF mice." (PMID 29892281, 2018). "The HFD group developed insulin resistance as shown by a slower lowering of blood glucose levels after insulin injection and a greater ITT AUC compared to the LFD group." (PMID 30054493, 2018). "A causal relationship between obesity and insulin resistance in T2DM is historically well established, and includes pioneering observations that insulin levels were greater in obese diabetic individuals than lean healthy counterparts." (PMID 30298053, 2018).
Insulin resistance (continued). "Akt inhibition worsens insulin resistance and hampers several pathways downstream of insulin stimulation, as observed in PCOS women whose treatment with high doses of DCIns was shown to be detrimental." (PMID 30595691, 2018). "We have previously demonstrated that high MGO levels lead to endothelial insulin resistance with impaired Akt-dependent pathway and NO release in response to insulin." (PMID 29425121, 2018). "It is important to mention that the high levels of FFAs not only induce hepatic insulin resistance but also impair insulin clearance, leading to hyperinsulinemia in insulin-resistant states and in patients with NAFLD." (PMID 30011790, 2018). "Effect of SCE on fasting serum insulin level and insulin resistance in diabetic rats (x ̄ ± SD, n = 8)." (PMID 29670524, 2018). "In the present study, it was observed that improved insulin resistance was significantly associated with higher baseline BMI, FBG, fasting insulin, and HOMA-β." (PMID 29524187, 2018). "Although TAGs are not signaling molecules, fatty acids produced during their synthesis or breakdown were shown to interfere with the intracellular insulin signaling pathway and contribute to the development of insulin resistance." (PMID 29940972, 2018). "A decrease in the protein levels that were involved in nutrient metabolism and insulin signaling pathway and by HFD feeding in insulin-responsive organs including the liver, adipose tissue, and skeletal muscle can lead to the development of insulin resistance." (PMID 29783731, 2018). "Insulin resistance is an abnormal physiological state that occurs when insulin cannot trigger signaling pathways in target organs, such as the liver, adipose tissues, and muscles." (PMID 30478313, 2018). "The aims of the present study were to examine the effects of RSV on FOXO gene expression, serum superoxide dismutase (SOD) activity, insulin level, and insulin resistance in type 2 diabetic (T2DM) rats." (PMID 31565649, 2018). "Insulin resistance, defined as decreased sensitivity to metabolic actions of insulin, is important component of cardiovascular disorders, through decreased production of endothelial nitric-oxide-induced endothelial dysfunction." (PMID 30011841, 2018). "The first study demonstrated that mitochondrial dysfunction induced by hyperglycemic condition impaired the AMPK-Akt pathway which is a downstream signaling cascade of the insulin signaling pathway and contributed to insulin resistance." (PMID 30233495, 2018). "This can be attributed to altered glucose metabolism, impaired insulin signaling, and insulin resistance." (PMID 29324783, 2018). "Since DIO mice have both peripheral and central insulin resistance, it is possible that improved systemic insulin sensitivity and glucose homeostasis play some role in the amelioration of the behaviors of HFD-fed mice treated with antibiotics." (PMID 29910467, 2018). "Despite a lack of association with indices of beta-cell function in the Inter99 study, we did find an association with lower disposition index as an indication of a decreased beta cell secretion of insulin at the concomitant level of insulin resistance." (PMID 30292239, 2018). "There was evidence of worsening of insulin resistance markers withsignificantly increased fasting insulin and HOMA-IR; and decreased QUICKI in theobese group, compared to the eutrophic group." (PMID 29617475, 2018). "Plasma glucose and RBP4 concentration (an adipokine related to insulin resistance) remained stable during pregnancy, and insulin concentration and HOMA index only increased at 32 weeks of pregnancy." (PMID 30127377, 2018). "As a consequence, T2DM ensues due to systemic insulin resistance and relatively diminished insulin secretion from pancreatic β cells." (PMID 30483273, 2018).
Insulin resistance (continued). "In contrast, overexpression of PRDX-3 can reduce the levels of oxidative stress and alleviate insulin resistance, highlighting that oxidative stress plays a key role in maintaining insulin sensitivity." (PMID 30302116, 2018). "These are typically patients with advanced type 2 diabetes with increased insulin resistance and impaired peripheral insulin sensitivity, respectively, which has been repeatedly associated with adverse cardiovascular outcome and a high mortality rate." (PMID 30564289, 2018). "Triglycerides, insulin, homeostasis model assessment-insulin resistant (HOMA-IR), leptin, C-reactive protein (CRP), and EDF marker intercellular adhesion molecule 1 (ICAM-1) were significantly higher in obese children and adolescents." (PMID 30572569, 2018). "Insulin resistance generates oxidative stress on insulin-responsive tissues, enhanced autophagy in these cases acts as a protective factor." (PMID 29950970, 2018). "The main pathogenesis of T2DM includes insulin resistance and insufficient insulin production of pancreatic β cells, which lead to the disability to control glucose level in the circulation." (PMID 29785210, 2018). "T2DM is a non-insulin-dependent diabetes that is characterized by abnormal insulin secretion and insulin resistance because of pancreatic dysfunction." (PMID 30337946, 2018). "They found that reduced ATGL expression led to improved FBG, oral GTT, greater hepatic insulin signaling and decreased insulin resistance." (PMID 34466413, 2018). "Glucocorticoid serves as an insulin antagonist that regulates insulin resistance and glucose intolerance." (PMID 29765322, 2018). "PPARγ ligands, including TZDs, have hypoglycemic effects, reduce insulin resistance, and improve insulin sensitivity." (PMID 29747466, 2018). "GRK2 is also involved in insulin signaling/IR dysfunction in other tissue as its levels are increased in muscle and adipose tissue in the animal models of insulin resistance as well as in lymphocytes from patients with metabolic syndrome." (PMID 30147654, 2018). "T2DM is a common chronic metabolic disease resulting from insulin resistance, impaired insulin secretion or both." (PMID 30210342, 2018). "SBP has been reported to relieve spontaneous hypertension, protect pancreatic β-cells, improve insulin resistance and enhance the activity of insulin." (PMID 29551973, 2018). "Previous studies have shown that IGFBP-1 induced improved glucose regulation and increased insulin sensitivity is a part of protective mechanism induced upon insulin resistance in the body." (PMID 30627105, 2018). "The low dose of HK L-137 in particular improved systemic inflammation and LV diastolic function, reduced subcutaneous fat mass, as well as attenuated systemic insulin resistance and improved insulin signaling in both visceral and subcutaneous adipose tissue." (PMID 29802339, 2018). "While PPAR-γ-KO animals show embryonic lethality dying at 10.5–11.5 days postcoitum due to placental dysfunction, PPAR-γ heterozygote KO are characterized by higher insulin sensitivity and resistance to high-fat diet-induced insulin resistance." (PMID 29662003, 2018). "In the state of adipose insulin resistance, normal levels of insulin are unable to stimulate adipose glucose and lipid uptake and suppress triglyceride hydrolysis, due to inability of insulin to stimulate the down-stream IRS/PI3K/Akt pathway." (PMID 29473848, 2018). "Adipocytes are involved in the development of insulin resistance, resulting from the dysfunction of insulin signalling pathway." (PMID 30445784, 2018). "This ectopic lipid deposition significantly interferes with intracellular insulin signaling in these tissues, leading to insulin resistance." (PMID 29601521, 2018). "Cinnamon extract has been found to mitigate insulin resistance induced by high fructose diets and benefit glucose utilization by enhancing insulin signaling pathway." (PMID 30340496, 2018).